H19 (H19 imprinted maternally expressed transcript)
Diseases named in the same sentence as H19 in open-access papers (continued):
Sharing a sentence is not in itself a finding about the gene and the disease.
melanoma (26 papers, 2017 to 2025). A malignant, usually aggressive tumor composed of atypical, neoplastic melanocytes. "H19 is associated with poor prognoses, which means it could be a novel therapeutic target for melanoma." (PMID 34421359, 2021). "The analysis of the literature showed that HOTAIR, MALAT1, and H19 are the oncogenic lncRNAs most studied in melanoma, while MEG3 is an important tumor suppressor decreased in this cancer." (PMID 40282449, 2025). "One of the lncRNAs that showed significantly higher expression in the serum of melanoma patients is H19." (PMID 38601651, 2024). "The authors indicated that the overexpression of lncRNA H19 in melanoma was correlated with poor prognosis in patients." (PMID 37627777, 2023). "Knockdown of H19 affects melanoma cell growth, invasion, migration, apoptosis, G0/G1 phase arrest and sensitivity to cisplatin." (PMID 36601121, 2022). "SchA inhibited cell proliferation and migration and increased cell apoptosis in the melanoma cell line A375 by downregulating the expression of H19, which in turn inactivated the PI3K/Akt signaling pathway by decreasing the phosphorylation of PI3K and Akt." (PMID 34977037, 2021). "Another study discovered that silencing H19 suppressed melanoma cell migration and invasion by deactivating NF‐κB expression via the PI3K/Akt pathway." (PMID 34421359, 2021). "H19 silencing has increased the sensitivity of melanoma cells to cisplatin, suppressed colony formation, and enhanced apoptosis of cisplatin-resistant melanoma cells." (PMID 33768092, 2021). "H19 is significantly more highly expressed in melanoma tumor tissue than in adjacent healthy tissue." (PMID 34977037, 2021). "Recently, studies have demonstrated that the level of H19 expression is correlated with the migration and invasion of melanoma cells by regulating the activation of the PI3K/Akt signaling pathway." (PMID 34977037, 2021). "For instance, H19 silencing has enhanced the sensitivity of cancer cells to cisplatin and increased apoptosis of cisplatin-resistant melanoma cells through modulation of IGF1 expression." (PMID 33768092, 2021). "Overall, these data indicated that H19 had an oncogenic role in melanoma and represented a novel therapeutic target." (PMID 34421359, 2021). "H19 is a long non-coding RNA, and its abnormal expression has been found in various tumors, including melanoma." (PMID 31649871, 2019). "Zhu and colleagues showed that H19 promotes the proliferation, invasion, and growth of melanoma cell line A375 by upregulating Akt phosphorylation, increasing the expression of matrix metalloproteinases 2 (MMP2), MMP9, and Slug and downregulating the expression of E-cadherin." (PMID 34977037, 2021). "In malignant melanoma, expression of the lncRNA H19 was shown to be increased in melanoma tissue and might function as a sponge of miR-106a-5p to upregulate E2F3 expression and consequently promote the glucose metabolism and growth of melanoma cells." (PMID 32765426, 2020). "Thus, lncRNA H19 may serve as a survival indicator and potential therapeutic target for melanoma patients." (PMID 37627777, 2023). "Likewise, H19 exerts an important role in melanoma by regulating the NF-kB signaling pathway." (PMID 34977037, 2021). "Downregulation of H19 could increase the sensitivity of melanoma cells to DDP." (PMID 33768092, 2021). "The expression of H19 imprinted maternally expressed transcript lncRNA is increased in melanoma tissues and cell lines and high H19 level has been associated with advanced tumor invasion and TNM stage, distal and lymph node metastases and shorter OS in patients with melanoma." (PMID 34638331, 2021). "Moreover, H19 knockdown inhibits melanoma cell proliferation, migration and invasion." (PMID 34977037, 2021).
melanoma (continued). "Therefore, H19 is a potential target for the treatment of melanoma." (PMID 34977037, 2021). "Broadly viewed, our literature analysis revealed that HOTAIR, H19, and MALAT1 are the main oncogenic lncRNAs studied, and correlated to the aggressiveness of melanoma phenotype and in the acquisition of drug resistance." (PMID 40282449, 2025). "Downregulation of lncRNA H19, which regulates the miR-18b/IGF1 axis, is said to make melanoma cells more sensitive to the effects of DDP, which is in agreement with our findings." (PMID 37361693, 2023). "H19 plays a critical role in regulating tumor plasticity in neuroendocrine prostate cancer, while SFRP2 in the aged microenvironment drives melanoma metastasis and therapy resistance." (PMID 37795080, 2023). "Functionally, downregulation of H19 mediates the inhibition of the PI3K/AKT signaling pathway and NF-κB signaling pathway, thereby inhibiting the progression of melanoma." (PMID 36601121, 2022). "The lncRNAs H19 and CCAT1, instead, control melanoma cell invasion in vitro and tumor growth in vivo by regulating glucose metabolism." (PMID 35159386, 2022). "They found that H19 acts as a sponge for miR-106a-5p, leading to the upregulation of E2F3 transcription factor expression in melanoma cells." (PMID 33652661, 2021). "H19, NR2F1-AS1, and SNHG7 participate in the development of melanoma and breast cancer through modulation of IGF1." (PMID 33768092, 2021). "H19 via acting as a molecular sponge of miR-18b can regulate IGF-1 expression and sensitivity of melanoma cells to DDP." (PMID 33768092, 2021). "Other than that, ROR1, FOXC1, MIF, TGFβ, lncRNA SNHG17, MIAT, MHENCR, OR3A4 and H19 regulate proliferation, progression, migration, invasion, metastasis or EMT-like transition though PI3K/AKT pathway in melanoma cells." (PMID 32333246, 2020). "Another study also demonstrated that lncRNA H19 predicts poor prognosis in patients with melanoma and regulates cell growth, invasion, migration, and epithelial-mesenchymal transition (EMT) in melanoma cells." (PMID 31649871, 2019). "Several studies have identified known lncRNAs that are abnormally expressed in melanoma, such as SAMMSON, HOTAIR, SLNCR1, BANCR, SPRY4-IT1, ANRIL, Llme23, UCA1, MALATA1, GAS5, H19, CASC15, PTENP1, and MIR31HG." (PMID 28225791, 2017). "Similarly, a separate study analyzing the knockdown of lncRNA H19 found a reversal of EMT in melanoma cell lines, suggesting H19 plays a role in promoting EMT and thus melanoma cell invasion." (PMID 37629553, 2023). "Finally, the lncRNAs XIST, H19, MEG3, and LINC01291 were shown to confer resistance of melanoma cells to platinum compounds by regulating miR-21/PI3KR1 miR-18/IGF1, miR-499-5p/CYLD, and miR-625-5p/IGF-1R axis, respectively." (PMID 35159386, 2022). "Moreover, H19 functions as a sponge for miR-106a-5p, a tumor suppressor miRNA that targets E2F3, and miR-18b that targets IGF1 H19-mediated upregulation of E2F3 promotes glucose metabolism and growth of melanoma cells." (PMID 34638331, 2021).
osteosarcoma (26 papers, 2016 to 2026). A usually aggressive malignant bone-forming mesenchymal neoplasm, predominantly affecting adolescents and young adults. "In an in vitro model of Li-Fraumeni syndrome- associated osteosarcoma, iPSC-derived from patients generated osteoblasts that recapitulated osteosarcoma features and exhibited decreased H19 gene expression relative to wild-type controls." (PMID 34299287, 2021). "Gao and Lian reported that lncRNA MALAT1 was an independent prognostic factor of osteosarcoma, and another lncRNA, H19, was also proved to be associated with osteosarcoma progression." (PMID 34456631, 2021). "In summary, our findings demonstrate a critical role of H19-modulated SNORA7A expression in LFS-associated osteosarcomas." (PMID 33519915, 2020). "In conclusion, our study indicated that lncRNA H19 plays a vital regulatory role in inhibiting osteosarcomagenesis and provides mechanistic insights for improving our understanding of H19-mediated tumor suppression in LFS patient-associated osteosarcomas." (PMID 33519915, 2020). "Silencing of Wnt inhibitory factor 1(WIF1), p14ARF, and RASSF1A by DNA hypermethylation and loss-of-imprinting in IGF2 and H19 have also been shown to occur in osteosarcoma." (PMID 26802029, 2016). "The specific loss of imprinting at the 14q32 and H19 loci in osteosarcoma samples suggested that these methylation changes were disease-specific and not the result of global methylation changes." (PMID 26802029, 2016). "Osteosarcoma cell migration and invasion have been significantly reduced by H19 knockdown, which may be associated with inactivation of the NF-κB signaling pathway." (PMID 34977037, 2021). "Moreover, H19 has been associated with distant metastasis of osteosarcoma and overall survival of patients with osteosarcoma." (PMID 34977037, 2021). "We investigated the tumor suppressor function of lncRNA H19 in LFS-associated osteosarcoma." (PMID 33519915, 2020). "In vitro, targeting H19 by RNA interference (RNAi) has been demonstrated to reduce osteosarcoma cell migration and invasion by modulating the NF‐κB pathway." (PMID 41521159, 2026). "On the other hand, H19 was also reported to increase proliferation in osteosarcoma cells by acting as a competing endogenous non‐coding RNA sponging microRNAs." (PMID 41521159, 2026). "Previous in vivo studies have evaluated the prognostic and biological influence of H19, mainly in osteosarcoma and rhabdomyosarcoma, and arrived at partially divergent conclusions regarding the functional role of H19." (PMID 41521159, 2026). "in osteosarcoma align with our prognostic in vivo data, demonstrating that low H19 expression promotes sarcoma pathogenesis." (PMID 41521159, 2026). "Aberrant Hh signaling induces the expression of Yap1 and H19 during the development of osteoblastic osteosarcoma." (PMID 40624028, 2025). "In osteosarcoma cells, galic acid down-regulates lncRNA H19 expression, disrupting Wnt/β-catenin signaling and impeding osteosarcoma development." (PMID 39045282, 2024). "In osteosarcomas, an abnormal degree of H19 expression has been detected, which can be promoted by amplified Hedgehog (Hh) signaling and upregulated yes-associated protein 1 (Yap1)." (PMID 39015175, 2024). "Gallic acid inhibits tumor growth in osteosarcoma cells through the H19-mediated Wnt/β-catenin signaling regulatory axis." (PMID 39015175, 2024). "The overexpression of YAP1 and H19 is responsible for the pathogenesis of osteosarcoma, indicating a positive relationship between YAP1 and H19." (PMID 34401209, 2021). "H19 was significantly overexpressed in osteosarcoma tumor tissue compared with adjacent healthy tissue." (PMID 34977037, 2021). "H19 regulates osteosarcoma cell processes by acting on the NF-κB signaling pathway, and as one of the mechanisms, H19 has been investigated." (PMID 34977037, 2021).
osteosarcoma (continued). "Increasing evidence has shown that the H19 is involved in the development of osteosarcoma, and the mechanisms are more complex and need further investigation." (PMID 34977037, 2021). "H19 knockdown apparently increases the level of IκBα by regulating the activation of the PI3K/Akt signaling pathway in osteosarcoma cell lines compared with normal cells." (PMID 34977037, 2021). "Decreased human osteosarcoma cell viability and downregulated H19 occurs after the inhibition of the hedgehog signaling pathway or knockdown of the Yap1 gene." (PMID 28353666, 2017). "In both osteosarcoma tissues of human primary and mouse xenograft origins, H19 was highly upregulated." (PMID 28353666, 2017). "Based on a 95% confidence interval of normal bone tissue, ~59% (19 out 32) of osteosarcoma samples showed imprinting defects at H19-DMRs." (PMID 26802029, 2016). "Compared to osteosarcoma, the role of H19 in rhabdomyosarcoma has been less extensively studied." (PMID 41521159, 2026). "However, only a few studies have explored the clinical and biological role of H19 in soft tissue sarcoma pathogenesis, as almost all previous H19 studies focused on osteosarcoma." (PMID 41521159, 2026). "The authors identified H19 as critical to osteogenic dedifferentiation in osteosarcoma." (PMID 41521159, 2026). "Ectopic expression of H19 expression in Li-Fraumeni syndrome osteoblasts aided osteoblast differentiation and suppressed tumorigenic potential, elucidating the novel role for the H19-Decorin pathway in suppressing osteosarcoma." (PMID 34299287, 2021). "While H19 has been demonstrated in various contexts to act as either a tumor suppressor or an oncogene, our current work further demonstrates the important regulatory role of H19 in osteosarcoma initiation and progression." (PMID 33519915, 2020). "However, the protein complexes tethered by H19 in osteosarcoma remain largely unknown." (PMID 33519915, 2020). "In our previous studies, using a LFS patient-derived iPSC model, we demonstrated the tumor suppressor role of lncRNA H19 and the oncogenic role of SFRP2 during the formation of osteosarcoma in LFS patients." (PMID 33519915, 2020). "With regard to osteosarcoma, lncRNAs such as HOTAIR, HULC, H19 and MALAT-1, have been identified to be aberrantly expressed in cancer and function with underlying mechanisms." (PMID 31443665, 2019). "H19 has also been shown to function as a tumor suppressor to promote osteogenesis and inhibit osteosarcomagenesis in LFS osteoblasts and osteosarcoma, implying that IACS-010759 may shift cells from a tumorigenic and undifferentiated profile towards normal osteoblast differentiation." (PMID 34965247, 2021).
Stroke (26 papers, 2017 to 2025). Sudden impairment of blood flow to a part of the brain due to occlusion or rupture of an artery to the brain. "The plasma expression level of lncRNA H19 is of potential clinical diagnostic value for stroke, and the circulating lncRNA H19 expression level was significantly upregulated in stroke patients compared with that in healthy controls." (PMID 36420646, 2022). "Another independent study revealed that lncRNA H19 levels were significantly increased in the blood and cytoplasm of stroke patients, with high diagnostic sensitivity and specificity levels." (PMID 36132228, 2022). "In the current study, the diagnostic potential of lncRNA H19 level as a biomarker in IS patients was evaluated by ROC curve analysis and were compared at different times after stroke." (PMID 33541284, 2021). "Another independent research indicated that the lncRNA H19 levels elevated profoundly in stroke patients’ blood and cell plasma with high diagnostic sensitivity and specificity." (PMID 29651234, 2018). "We next determined H19 gene polymorphism in the blood sample from stroke patients to test the role of H19 gene polymorphism in the regulation of lncRNA H19 expression, since it’s hard to get human brain tissue sample." (PMID 28203482, 2017). "To gain insight into the role of lncRNA H19 in clinic, we examined H19 gene polymorphism in the blood sample of stroke patients, since it is impractical to have human brain samples." (PMID 28203482, 2017). "Furthermore, lncRNA H19 has been identified as a key player in various physiological and pathological processes linked to stroke, including inflammation, apoptosis, autophagy, and neurogenesis." (PMID 39161158, 2024). "This study demonstrated that the circulating H19 in the first 24 h after a stroke might be a diagnostic biomarker for IS." (PMID 33541284, 2021). "Plasma H19 levels are negatively associated with the prognosis of stroke." (PMID 33101034, 2020). "Specifically, PPARα KO led to increased expression levels of Gadd45b, Nppa, Hdc, Lcn2, Il6, Sox4, Marcksl1, Saa3, Ucn2, Met, Dusp10, Elovl7, Ngf, C3, Il11, Hmox1, Alox5, Tnfsf9, Angptl4, Plin2, H19, Csf2rb, Atf3, and Col7a1 following stroke." (PMID 40362325, 2025). "The results showed that lncRNA H19 plasma expression level was correlated with the risk of stroke in patients with AF, which could significantly improve the ability to predict the risk of stroke in patients with AF, and was a potential prognostic monitoring marker." (PMID 37522088, 2023). "To further elucidate the clinical significance of H19 and miR‐29b in patients with stroke, we analyzed the correlation of clinical parameters with H19 and miR‐29b expression." (PMID 35322553, 2022). "A clinical study has shown that the expression levels of lncRNA H19 in patients increase within the first 24 h of stroke onset, which is closely related to the rs217727 functional polymorphism." (PMID 35815278, 2022). "On the other hand, in contrast to the proposed neuroprotective effect of H19 silencing, another study suggests that H19 acts as mediator of stroke-induced neurogenesis." (PMID 35946958, 2022). "Considering the increased expression of H19 in patients with stroke, we further evaluated the role of H19 in cerebral ischemic injury in rats by intravenous injection of H19 siRNA three days before MCAO surgery." (PMID 35322553, 2022). "More profoundly, silencing or knockout of the H19 gene can improve the neurological outcome in the rodent MCAO stroke model." (PMID 34707480, 2021). "Circulating H19 levels within the first 24 h after the onset of a stroke indicated high sensitivity and specificity for the early diagnosis of acute stroke." (PMID 33541284, 2021). "We evaluated H19 expression at three different times (0–24 h [n = 39], 24–48 h [n = 38], and 48–72 h [n = 37] after stroke)." (PMID 33541284, 2021).